FOXA1 (forkhead box A1)
Diseases named in the same sentence as FOXA1 in open-access papers (continued):
Sharing a sentence is not in itself a finding about the gene and the disease.
prostate carcinoma (296 papers, 2007 to 2026). A carcinoma that arises from epithelial cells of the prostate gland. "FOXA1 is a prostate lineage-specifying transcription factor that is frequently dysregulated or mutated in prostate cancer (PCa)." (PMID 41904157, 2026). "Mutations in the pioneer transcription factor FOXA1 occur in 10%-40% of prostate cancers and broadly alter chromatin accessibility." (PMID 41621066, 2026). "AU-15330 is a highly selective degrader targeting SMARCA2 and SMARCA4, which induces a specific loss of chromatin accessibility at enhancers in prostate cancer cells driven by AR and FOXA1." (PMID 40032852, 2025). "Our finding is in consistency with prior work showing that non-coding mutations accumulating in prostate cancer are likely perturb the binding affinity of FOXA1 as well as alter the AR cistromes." (PMID 41468516, 2025). "Prostate cancer exhibited the greatest proportion of FOXA1 alterations, with 14.2% of tumors harboring mutations and 1.8% showing amplifications." (PMID 39745364, 2025). "At a mutation prevalence of 10% to 15%, FOXA1 is one of the most frequently altered genes in prostate cancer." (PMID 39745364, 2025). "Studies annotating the landscape of FOXA1 mutations from 3086 human prostate cancers, defined two hotspots in the forkhead domain Wing2 and the highly conserved DNA-contact residue R219." (PMID 41023204, 2025). "Among the downregulated epigenetic factors, Foxa1, which associates with the regulation of prostate cancer lineage plasticity, was identified." (PMID 39743630, 2025). "FOXA1 is another important transcription factor that is often mutated in multiple types of malignancies including prostate cancer." (PMID 40356745, 2025). "We next considered how each class of FOXA1 alteration associated with outcomes based on the first instance of prostate cancer systemic treatment by first-line ADT, second-generation AR signaling inhibitors (ARSI), and taxane chemotherapies." (PMID 39745364, 2025). "FOXA1 mutations are common in prostate cancer, and the investigators showed that cancer-associated and loss-of-function mutations affecting residue F254 promoted the dedifferentiation of adult prostate progenitors." (PMID 40362593, 2025). "FOXA1 is altered in ~12% of prostate cancer patients, predominantly through single-residue variants and short indels (~8.5% of cases)." (PMID 39633177, 2025). "Mutations in FOXA1 are observed in nearly half of primary prostate cancer tumors in Asian men and 20% of tumors in men of other ethnicities." (PMID 40356745, 2025). "Studies have shown that Asian populations exhibit higher mutation rates of SPOP and FOXA1 in prostate cancer, while European populations are more characterized by ERG fusion mutations and PTEN loss." (PMID 39882449, 2024). "Landmark genomic studies have revealed that FOXA1 is among the most frequently-mutated genes in prostate cancer patients." (PMID 38528115, 2024). "HypoDMRs in prostate tumors of EA men were enriched for previously known prostate cancer-associated transcription factors, including FOXA1 and AR." (PMID 38566104, 2024). "Given repeated observations of FOXA1 mutations in prostate cancer, we were also motivated to investigate the implications of clinically-observed mutations in FOXA1 on SEMA3C expression." (PMID 38528115, 2024). "Sema3C also seems to be involved in the progression of prostate cancer via the mutation of the transcription factor FOXA1 and even contributes to its resistance to therapy." (PMID 39457718, 2024). "Meanwhile, mutation of FOXA1 alters the tumor environment significantly so that it is regarded as a driver gene of prostate cancer." (PMID 37958805, 2023). "Changes in FOXA1 (forkhead box protein A1) protein levels are well associated with prostate cancer (PCa) progression." (PMID 37491794, 2023). "Mutations of the Forkhead box A1 (FOXA1) gene have been linked to unique oncogenic features in prostate cancer." (PMID 37958805, 2023).
prostate carcinoma (continued). "While these drugs have been used to treat specific types of prostate cancer, there is a gap in research specifically addressing their efficacy in the context of FOXA1 mutation." (PMID 37958805, 2023). "Although numerous reports have demonstrated the role of FOXA1 in both in vitro and in vivo prostate cancer models, the precise role and impact of FOXA1 mutations in primary prostate cancer and tumor microenvironment remain to be fully elucidated." (PMID 37958805, 2023). "Meanwhile, FOXA1 was reported to be associated with multiple kinds of cancers, especially prostate cancer (PCa) and BC." (PMID 38044421, 2023). "Among the key genetic alterations observed in prostate cancer, mutations in the FOXA1 gene have been found in up to 9% of primary prostate cancer cases and have gained considerable attention." (PMID 37958805, 2023). "It is noteworthy that the mutation ratio of FOXA1 in castration-resistant prostate cancer (CRPC) is significantly higher compared to primary prostate cancer." (PMID 37958805, 2023). "Digging deeper into immune-related pathways, we identified six pathways associated with immune inactivation in FOXA1 mutant prostate cancer." (PMID 37958805, 2023). "While additional validation is required to elucidate the specific impact of FOXA1 mutation on these immune-related pathways, our findings propose that FOXA1 mutation in prostate cancer leads to alterations in tumor-associated immune systems." (PMID 37958805, 2023). "FOXA1 (Forkhead box protein A1), in particular, is frequently mutated, occurring in up to 9% and 13% of cases of primary prostate cancer and metastatic castration-resistant prostate cancer (mCRPC), respectively." (PMID 37958805, 2023). "Meanwhile, Labbé and Brown identified the association between FOXA1 and castration-resistant prostate cancer." (PMID 35498155, 2022). "For example, the loss of FOXA1 increased the level of transforming growth factor-beta 3 (TGFβ3) and activated TGFβ signaling pathway in prostate cancer." (PMID 36012038, 2022). "This is accompanied by the loss of DNA binding of several key transcription factors in prostate cancer progression, including the AR, FOXA1 and ERG." (PMID 36212399, 2022). "In particular, it would be useful to characterize the universal subset of FOXA1 interactions in prostate cancer tumorigenesis as well as molecular changes associated with mutated forms of FOXA1." (PMID 35550030, 2022). "Overall, this study reveals that loss of Foxp1 increases cell proliferation, whereas loss of Foxa1 induces epithelial plasticity in prostate cancer." (PMID 36139541, 2022). "The family of Forkhead box (FOX) transcription factors are often altered in prostate cancer with especially high mutation burden in FOXA1 and FOXP1." (PMID 36139541, 2022). "FOXA1 harbors loss or gain of function mutations in 8% of prostate cancer, which increases to 14% in metastatic samples." (PMID 36139541, 2022). "Mutations in the FOXA1 gene have been recurrently reported in prostate cancer, ER-positive breast cancer, and liver cancer." (PMID 35273656, 2022). "FOXA1 is mutated in 3–12% of primary and advanced prostate cancers, and several of these mutations alter the genome interaction and affect differentiation programs." (PMID 35682963, 2022). "The finding of Jin’s group illustrated that recurrent mutation of FOXA1 lead to prostate carcinoma progress." (PMID 36292640, 2022). "The mutations of FOXA1 altered its pioneering activity, perturbing normal luminal epithelial differentiation programs and prompting prostate cancer progression." (PMID 36050295, 2022). "It has been also suggested that NANOG associates with androgen receptor (AR) and FOXA1 to regulate pro‐differentiation genes and castration resistance in prostate cancer." (PMID 33439550, 2021).
prostate carcinoma (continued). "This is consistent with the importance of such domains in guiding the regulatory functions of transcription factors as well as with previous characterizations of the functional divergences present within FOXA1 mutations in prostate cancer cohorts." (PMID 33957863, 2021). "The expression levels of DPP4 based on gleason score 9 group, N1 nodal metastasis group, and FOXA1 mutation group in prostate cancer tissues were lower than normal controls (all P < 0.001)." (PMID 33407865, 2021). "Chinese prostate cancer patients acquire mutations in FOXA1 at a high frequency (about 40%), as shown by a recent report." (PMID 34207505, 2021). "Genome-wide analysis of prostate cancer risk SNPs and somatic SNVs demonstrated that they converge and enrich at the binding sites of other master transcription factors besides FOXA1, including AR, HOXB13 and SOX9." (PMID 32946061, 2021). "FOXA1 is recurrently mutated in its coding sequence in up to 9% and 13% of primary prostate cancer and mCRPC, respectively." (PMID 32946061, 2021). "The study demonstrated that FOXA1 mutations can be readily detected in liquid biopsy and can potentially serve as a prostate cancer-specific biomarker." (PMID 32946061, 2021). "Recent studies reveal that FOXA1 is functionally altered by both coding and noncoding mutations which drives prostate cancer progression." (PMID 32946061, 2021). "Co-regulation of transcription by AR and FOXA1 in prostate cancer is associated with reprogrammed binding of AR and oncogenic patterns of gene expression that are essential for AR-driven proliferation." (PMID 33596994, 2021). "Our previous study confirmed that FOXA1 was frequently mutated in prostate cancer in an Asian cohort." (PMID 34513844, 2021). "FOXA1 mutations found across various stages of prostate cancer present an opportunity to track disease progression." (PMID 32946061, 2021). "A targeted sequencing of 72 prostate cancer driver genes in the plasma cell-free DNA of patients with mCRPC revealed 37 somatic mutations mapped to FOXA1 3′ UTR in 34/290 (12%) of the patients." (PMID 32946061, 2021). "In prostate cancer, mutations converge onto the coding sequence and cis-regulatory elements (CREs) of FOXA1, leading to functional alterations." (PMID 32946061, 2021). "Clustered activating mutations in FOXA1 have been classified into three categories in both breast and prostate cancers." (PMID 34680352, 2021). "FOXA1 coding mutations emerge throughout prostate cancer progression and cluster at hotspot regions that are important for FOXA1 protein function." (PMID 32946061, 2021). "Recent studies have also found that FOXA1 mutations affect the phenotype of prostate cancer and interfere with the differentiation of normal prostate epithelium." (PMID 34513844, 2021). "This would be consistent with a previous report that revealed higher expression of FOXA1 in prostate cancer than in normal prostate tissue that was associated with advanced stages of cancer." (PMID 32655839, 2020). "Taken together, FOXA1 is recurrently mutated taking into account both its coding and flanking noncoding sequences across various stages of prostate cancer development." (PMID 31974375, 2020). "Despite FOXA1 being recurrently mutated and playing potent oncogenic roles in prostate cancer etiology, the CREs involved in its transcriptional regulation are poorly understood." (PMID 31974375, 2020). "FOXA1 has been shown to be implicated in diverse cancer development, such as breast cancer, prostate cancer and bladder cancer." (PMID 32201519, 2020). "The FOXA1 gene in one of the genes most frequently mutated in prostate cancer, its mutation being more frequent in metastatic than in primary tumors." (PMID 31366128, 2019). "As above observed, some recent studies indicate that FOXA1 is a pioneer transcription factor essential for prostate gland development and frequently mutated in prostate cancer." (PMID 31366128, 2019).
prostate carcinoma (continued). "TransIndel enhanced the taxonomy of DNA- and RNA-level alterations in prostate cancer by identifying recurrent FOXA1 indels as well as exitron splicing in genes implicated in disease progression." (PMID 29673323, 2018). "This implicates the long non-coding gene AL121790.1 as a facilitator in two distinct prostate cancer driving mechanisms (FOXA1 mutations and ETV1 fusions)." (PMID 30272002, 2018). "In this study, we report mutation frequencies in the UTRs of 72 known prostate cancer driver genes in 428 men with mCRPC, and identify an indel-dominated pattern of somatic mutation encompassing the entire FOXA1 3′-UTR and C-terminal." (PMID 30272002, 2018). "For instance, FOXA1, which acts as a pioneering factor in prostate cancer, is found to be affected by cis-GoF mutations in the prostate cancer cell lines DU-145 and PC-3 and in the colon cancer cell line HT-29." (PMID 28854983, 2017). "FoxA1 determines AR genomic binding in cultured prostate cancer cells and is frequently mutated in human prostate cancer." (PMID 27374105, 2016). "This increased binding of FOXA1 can facilitate the recruitment of FOXA1‐dependent androgen receptor, which is associated with poor prognosis in prostate cancer." (PMID 26419725, 2016). "There is now ample evidence that the FoxA1 gene is mutated or amplified in some breast and prostate cancers." (PMID 25401090, 2014). "In their mini-review, Robinson and colleagues consider the accumulated evidence and provide insights into the implications of FoxA1 mutations in the context of breast and prostate cancers." (PMID 25401090, 2014). "Two large prostate cancer sequencing papers recently reported that FOXA1 mutations occur in 3.4–5.2% of tumors." (PMID 23420418, 2013). "Recently, another level of regulation has been described, with the discovery that FOXA1 is mutated in 1.8% of breast and 3–5% prostate cancers." (PMID 23420418, 2013). "Androgen-induced AR reprogramming is also observed after downregulation of FoxA1, a pioneer transcription factor involved in AR targeting and frequently mutated in prostate cancer, although the role of FoxA1 in CRPC remains to be determined." (PMID 23019221, 2012). "This is supported by a recent study in LNCaP prostate cancer cells where depletion of FOXA1 caused significant remodelling of AR binding patterns and a marked increase in androgen regulated transcripts." (PMID 22545144, 2012). "Early prostate cancer is largely characterized by the accumulation of single nucleotide variants (SNVs) in genes like forkhead box protein A1 (FOXA1) and ATM, along with deletion of tumor suppressor genes like NKX3-1 and retinoblastoma transcriptional corepressor 1 (RB1)." (PMID 40863429, 2025). "Similarly, the pioneer transcription factor FOXA1, which forms anti-heterochromatin condensates and activates tumor suppressor genes, is frequently mutated in breast and prostate cancers." (PMID 40507965, 2025). "Moreover, extensive studies, including our previous work, demonstrated that somatic mutations in prostate cancer frequently converge on the FOXA1/AR pathways." (PMID 41468516, 2025). "Through the interrogation of 5,014 prostate cancer samples, we found that FOXA1 alterations could be subdivided into three broad mutational mechanisms: missense mutations or in-frame indels, predicted truncating events, or gene amplifications." (PMID 39745364, 2025). "Studies showed that the loss of FOXA1 might play a role in the progression of prostate cancer to neuroendocrine prostate cancer." (PMID 41407823, 2025). "Under hypoxia, loss of FOXA1 attenuates androgen-responsive transcription while activating hypoxia-inducible genes, demonstrating a dual role for this axis in hypoxia adaptation and prostate cancer progression." (PMID 40643528, 2025).
prostate carcinoma (continued). "Furthermore, previous researches reveal that redistribution of key prostate cancer–associated TFs, AR and FOXA1, from epithelial‐associated to NE‐associated regulatory elements promote NE cell‐like lineage plasticity." (PMID 41415713, 2025). "Notably, this germline-driven convergence onto FOXA1/AR pathways parallels the well-established somatic mutations that also funnel into AR-regulated networks, underscoring a shared molecular axis of prostate cancer pathogenesis." (PMID 41468516, 2025). "However, despite the frequent recurrence of FOXA1 mutations in prostate cancer, the mechanisms by which FOXA1 variants drive its oncogenic effects are still unclear." (PMID 38528115, 2024). "Furthermore, the higher incidence of FOXA1 mutations in mCRPC compared to mCSPC and locoregional prostate cancer prompted us to investigate the underlying factors contributing to this disparity." (PMID 37584393, 2023). "In this study, we aimed to explore the molecular and cellular characteristics associated with FOXA1 mutant prostate cancer and identify potential therapeutic targets and candidate drugs that may hold promise for improved treatment approaches." (PMID 37958805, 2023). "FOXA1 also interacts with ARs, thus influencing their activity, and the increased expression of FOXA1 has been associated with a less favorable prognosis in prostate cancer patients." (PMID 37686423, 2023). "Also of interest were several genes associated with prostate cancer metastases including FOXA1, EZH2, SCHLAP1, CDH1, SOX4, SOX9, HOXB13, and TGFBR3." (PMID 38067373, 2023). "FOXA1 mutations in prostate cancer cells are reported to reduce the number of AR binding sites but replaces AR function by increasing the activities of AR target genes AR coactivators and FOXA1 are known to interact with AR by binding to numerous enhancers to increase AR signaling." (PMID 36937425, 2023). "In addition, we explored therapeutic targets by investigating FOXA1 interacting protein within proteins encoded by upregulated genes in FOXA1 mutant prostate cancer, and identified six genes—HSP90AB1, KDM1A, FKBP4, H2BC15, WNT7B, and GRB7." (PMID 37958805, 2023). "FOXA1 gene mutation inhibits androgen signaling in prostate cancer and promotes tumor growth." (PMID 36970364, 2023). "FOXA1 mutations alter pioneering activity, differentiation and prostate cancer phenotypes." (PMID 36704352, 2022). "The FOXA1 was identified as a recurrent mutation in prostate carcinoma by exome sequencing." (PMID 36292640, 2022). "However, loss of function studies of Foxa1 in the mouse prostate induces hyperplasia and shows that Foxa1 can have dual roles in prostate cancer." (PMID 36139541, 2022). "A more recent study showed that the reprogrammed AR cistrome observed in mCRPC coincides with sites already bound by FOXA1 in normal and primary tumor tissue, further supporting a model where FOXA1 pre-marks a cancer-associated AR cistrome to facilitate prostate cancer progression." (PMID 36212399, 2022). "Another mechanism of activating metastatic traits may come from changes in epigenetic alterations, such as the case of FOXA1 mutations in prostate cancer." (PMID 36230523, 2022). "FOXA1 expression is altered by noncoding mutations across prostate cancer stages." (PMID 32946061, 2021). "FOXA1 is also reported as the third most frequently mutated gene in prostate cancer." (PMID 32946061, 2021). "Despite some missing knowledge, EMT inhibition may be a novel strategy to treat metastatic prostate cancer with FOXA1 mutations." (PMID 32946061, 2021).